MGMT (O-6-methylguanine-DNA methyltransferase)
Description:
Involved in the cellular defense against the biological effects of O6-methylguanine (O6-MeG) and O4-methylthymine (O4-MeT) in DNA. Repairs the methylated nucleobase in DNA by stoichiometrically transferring the methyl group to a cysteine residue in the enzyme. This is a suicide reaction: the enzyme is irreversibly inactivated.
Tractability: Small molecule: a structure with a bound ligand is known; a high-quality ligand is known; it belongs to a druggable protein family. PROTAC: ubiquitination databases record sites on it; its protein half-life has been measured; a small molecule that binds it is known.
Target class: Enzyme; Transferase
Chemical probes: O6-Benzylguanine
Gene: Protein-coding gene on chromosome 10 (129,466,679 to 129,770,983, forward strand). Ensembl gene ENSG00000170430.
Subcellular location: Nucleus
Subcellular location (Human Protein Atlas): Nucleoplasm
Pathways (Reactome):
DNA Repair: MGMT-mediated DNA damage reversal
Gene Ontology:
Molecular function: DNA binding; DNA-methyltransferase activity; methylated-DNA-[protein]-cysteine S-methyltransferase activity; methyltransferase activity; catalytic activity
Biological process: negative regulation of apoptotic process; positive regulation of double-strand break repair; DNA repair
Cellular component: membrane; nucleoplasm; nucleus
Genetic constraint (gnomAD): Loss-of-function variants: 15 observed, 16.34 expected, observed/expected ratio (o/e) 0.92, 90% interval 0.61 to 1.41. The upper end of that interval is the gene's LOEUF score, 1.41, which puts it in group 5 of 6, group 1 being the genes least tolerant of losing a copy. Missense variants: 282 observed, 278.66 expected, observed/expected ratio (o/e) 1.01, 90% interval 0.92 to 1.12. Synonymous variants: 130 observed, 121.38 expected, observed/expected ratio (o/e) 1.07, 90% interval 0.93 to 1.24.
Homologues: Orthologues: chimpanzee MGMT (98% identical), macaque MGMT (93% identical), rabbit MGMT (74% identical), mouse Mgmt (70% identical), rat Mgmt (69% identical), pig MGMT (67% identical), guinea pig MGMT (66% identical), dog MGMT (64% identical), tropical clawed frog mgmt (46% identical), zebrafish mgmt (38% identical), Drosophila melanogaster agt (23% identical), Caenorhabditis elegans agt-1 (21% identical).
Diseases named in the same sentence as MGMT in open-access papers:
MGMT is named in the same sentence as 320 diseases in open-access papers, as found by Europe PMC text mining. Sharing a sentence is not in itself a finding about the gene and the disease. The quoted sentences say what the papers report.
glioblastoma (1,340 papers, 1997 to 2026). The most malignant astrocytic tumor (WHO grade IV). "Background/Objectives: Although O6-methylguanine-DNA methyltransferase (MGMT) promoter methylation is a key predictive biomarker in glioblastoma, its association with clinical and lifestyle characteristics remains poorly understood." (PMID 41682986, 2026). "Of all 26 MGMT methylated glioblastomas, twelve showed CDKN2A/B loss while 14 showed retained CDKN2A/B, and of all 19 MGMT unmethylated glioblastomas eight showed CDKN2A/B loss while 11 showed retained CDKN2A/B." (PMID 41438586, 2026). "Our findings suggest gross total resection of contrast-enhancing tumour and MGMT promoter methylation are strongly associated with improved survival following first recurrence of glioblastoma." (PMID 41530365, 2026). "Pathology results were consistent with recurrent glioblastoma (MGMT promoter methylated, TERT mutation positive)." (PMID 40778355, 2025). "In this study, we aimed to explore the role of intergenic and intragenic enhancer methylation in MGMT expression as well as its association with clinical parameters, including overall survival, genetic variants, and demographic factors in glioblastoma." (PMID 40244270, 2025). "Our findings suggest that a high THEMIS2 expression correlates with poorer survival in MGMT-methylated glioblastoma patients, potentially offsetting the survival advantage typically associated with MGMT methylation." (PMID 39851494, 2025). "Available data indicate that the elevated MGMT expression in glioblastoma and neuroendocrine neoplasms is associated with resistance to alkylating agents such as temozolomide (TMZ)." (PMID 41300971, 2025). "Taken together, these data identify USP7 as a key regulator of MGMT stability in the nucleus of glioblastoma (GBM) cells by counteracting K48-linked ubiquitination, offering mechanistic insights into MGMT regulation." (PMID 40835840, 2025). "Specifically, in the CGGA dataset, we observed that a high THEMIS2 expression was associated with poorer survival in patients with MGMT-methylated glioblastoma." (PMID 39851494, 2025). "Beyond inherited polymorphisms, somatic mutations in the MGMT gene are increasingly observed in several malignancies including glioblastoma and colorectal carcinoma." (PMID 40895460, 2025). "This applies to about 40% of glioblastoma, which are MGMT promoter methylated and therefore deficient in MGMT, having significant impact on therapeutic outcome." (PMID 41350483, 2025). "A key finding is that MGMT promoter hypermethylation is linked to a more favorable prognosis in glioblastoma, particularly when patients are treated with alkylating agents like temozolomide." (PMID 39834719, 2025). "Our results on clinical and demographic parameters corroborate with previous findings, indicating that MGMT enhancer methylation is associated with genetic variants, clinical parameters, and demographic characteristics in glioblastoma." (PMID 40244270, 2025). "Approximately 40–60% of glioblastomas show high methylation levels in the promoter of MGMT, the gene encoding O6-methylguanine-DNA methyltransferase." (PMID 40277764, 2025). "The status of O‐6‐methylguanine DNA methyltransferase (MGMT) promoter methylation is a critical prognostic factor in glioblastoma, as its methylation is associated with better response to alkylating agents like temozolomide, improving the overall survival." (PMID 41277375, 2025). "Patients with IDH-mutant tumors or methylated MGMT promoters generally have improved survival, while recurrent glioblastoma is associated with a median survival of only six months, as therapies in these cases are often palliative." (PMID 39796773, 2025).
glioblastoma (continued). "Recent findings indicate that methylation of CpGs in MGMT enhancers is associated with MGMT expression in glioblastoma." (PMID 40244270, 2025). "In one of the studies, in which 116 glioblastomas and 23 anaplastic astrocytomas were neuropathologically and molecularly examined, a correlation was found between MGMT promoter methylation and IDH mutation in 95% of cases." (PMID 40428422, 2025). "The Fstl1/DIP2A/MGMT pathway is linked to temozolomide resistance in glioblastoma, with increased Fstl1 expression contributing to resistance, while decreased expression enhances drug sensitivity." (PMID 40781854, 2025). "Our findings suggested significant differences in absolute DNA methylation levels between intergenic and intragenic enhancers and their associations with MGMT expression, clinical parameters, genetic variants, and demographic characteristics in glioblastoma." (PMID 40244270, 2025). "Pre-treatment with 26S-proteasome inhibitor bortezomib prior to temozolomide caused MGMT mRNA and protein depletion in glioblastoma cell lines, causing cell death in vitro and prolonging survival in orthotopic mice." (PMID 39518074, 2024). "The adjunctive use of metformin in high-grade glioblastoma has been associated with improved survival rates, particularly in patients with MGMT promoter methylation." (PMID 38891882, 2024). "This is supported by findings of Raman spectroscopy that have previously linked the MGMT methylation status in glioblastoma to metabolic and biochemical changes in lipids." (PMID 39006162, 2024). "As repair of chloroethyl adducts is mediated by MGMT, epigenetic silencing of MGMT via promoter methylation is associated with a favorable response to alkylating agents in glioblastoma patients." (PMID 38892179, 2024). "An emerging application of radiogenomics is using MRI imaging to detect the MGMT sequence associated with glioblastoma, contributing to PPM-guided prediction, diagnosis, and treatment strategies." (PMID 39529768, 2024). "Other groups, moreover, demonstrated the possibility of predicting the mutation of IDH1 and PTEN and the methylation of MGMT using radiological data, proposing a probabilistic neuroradiological atlas of different phenotypic glioblastomas." (PMID 39513861, 2024). "AI is used in glioblastoma detection, for the prediction of the overall survival (OS) rate, and for determining the MGMT promoter methylation status, which is a mutation positively associated with an improved prognosis and temozolomide treatment response." (PMID 38827949, 2024). "In the adjusted model, the associations with MGMT methylated promoter (OR 14.13, 95% CI 3.88–51.43), receiving a gross total/total microscopic resection (OR 2.73, 95% CI 1.01–7.33) and a glioblastoma diagnosis (OR 0.03, 95% CI 0.01–0.09) persisted." (PMID 39767640, 2024). "By contrast, the MGMT-promoter-methylation status, a well-known prognostic factor in glioblastoma, was associated with increased OS only in the CR group." (PMID 38668045, 2024). "The predictive value of MGMT deficiency in both prognosis and response to temozolomide in glioblastoma is well-established, which mainly occurs through the methylation of the promoter in patients with this tumor." (PMID 38347461, 2024). "For O6‐alkylguanine DNA alkyltransferase (MGMT) was one of the most important chemo‐resistance associated protein, we evaluated MGMT expression in glioblastoma cells before and after co‐culturing with TAAs, which disclosed no obvious change." (PMID 38332576, 2024). "Equally important to the biomarker IDH1 mutation is MGMT gene silencing by methylation, which is found in about 50% of all newly diagnosed glioblastoma." (PMID 39767640, 2024). "MGMT methylation acts as a predictive biomarker for overall survival in unresectable IDH-wildtype glioblastoma patients undergoing systemic therapy following a diagnostic biopsy." (PMID 39367282, 2024).
glioblastoma (continued). "Cox regression analysis revealed that metformin was associated with a reduced risk of death at 2 years among patients with glioblastoma harboring a methylated MGMT promoter." (PMID 38891882, 2024). "Temozolomide, an alkylating agent, is a critical component of chemotherapy regimens for glioblastoma and works by promoting methylation of O6-methylguanine-DNA methyltransferase (MGMT), a DNA repair enzyme associated with treatment resistance." (PMID 39272576, 2024). "Radiotherapy combined with Temozolomide (TMZ) improves outcomes in patients with malignant glioblastoma; however, O6-methylguanine-DNA methyltransferase (MGMT)-mediated DNA restore causes TMZ resistance." (PMID 39228402, 2024). "With the modified RANO criteria, the rate of treatment-associated changes was low compared to previous studies in MGMT promoter-methylated glioblastoma." (PMID 38219019, 2024). "It is noteworthy that, in glioblastomas, high-methylation status of the MGMT promotor was associated with stronger fluorescence than low-methylation status." (PMID 39123426, 2024). "Temozolomide (TMZ), a standard component of glioblastoma treatment regimens, shows therapeutic efficacy closely linked to the methylation status of O6-methylguanine-DNA methyltransferase (MGMT)." (PMID 39716317, 2024). "An extensively studied epigenetic mechanism that regulates disease progression in glioblastoma is MGMT, which encodes the DNA repair protein O6-alkylguanine (O6-AG) DNA alkyl transferase (AGT)." (PMID 38928445, 2024). "The study established the MGMT promoter methylation as therapeutic marker as temozolomide chemotherapy was associated with a longer event-free survival in MGMT promoter methylated glioblastoma as compared to radiation therapy alone." (PMID 38032426, 2023). "Two genes, AC017104.4 and UNC93B7, were found to be specific for patients with IDH1-wt, TERT-promoter-mutated, and MGMT-methylated glioblastoma." (PMID 37568598, 2023). "Our aim was to focus on the outcome of glioblastoma patients and, thus, to search for DNA alterations of MGMT that are associated with survival." (PMID 37641156, 2023). "MGMT promoter methylation occurs in 40% of primary glioblastoma cases and is associated with increased survival after radiotherapy and chemotherapy with temozolomide." (PMID 36826144, 2023). "More interestingly, TCGA data mining confirmed that high expression of miR-93 was associated with better survival in the MGMT-methylated cohort of glioblastoma patients." (PMID 38239396, 2023). "It is important to note that in MGMT-deficient glioblastoma cells the effects of low doses accumulate with repetitive treatments." (PMID 38068493, 2023). "Loss of MGMT expression has been described in many tumor types, including glioblastoma, lymphoma, breast and prostate cancer, and retinoblastomas, and its usually due to promoter methylation." (PMID 36672401, 2023). "It is in accordance with previous reports which found only marginal associations between the methylation status of MGMT promotor and mRNA or protein expression levels in glioblastoma patients." (PMID 36906590, 2023). "The methylation of the O6-methylguanine-DNA methyltransferase (MGMT) promoter is a molecular marker associated with a better response to chemotherapy in patients with glioblastoma (GB)." (PMID 38203308, 2023).
glioblastoma (continued). "MGMT promoter methylation is significantly associated with tumor response to temozolomide in glioblastoma multiforme and NETs." (PMID 35677534, 2022). "Based on WHO 2021 classification and other previous reports has already established that Chr7 gain & Chr10 loss, TERT mutation along with EGFR expression and MGMT promoter methylation are the strongest predictor of survival in glioblastomas." (PMID 35144680, 2022). "One hallmark in glioblastoma therapy was the identification of MGMT promoter methylation that is associated with good therapy response using the alkylating agent temozolomide and with better outcome." (PMID 35453544, 2022). "The researchers focused on increased MGMT (O6-methylguanine-DNA methyltransferase) expression regulated by lncRNA TALC (temozolomide-associated lncRNA in glioblastoma recurrence) in TMZR cells." (PMID 36246634, 2022). "In a glioblastoma/anaplastic astrocytoma cohort of 80 tumors, standard molecular diagnostic procedures were conducted, including MGMT promoter methylation analysis using two methylation-specific PCRs (MSP) and pyrosequencing." (PMID 35180887, 2022). "MGMT promoter methylation at CpG sites upstream from CpG 82 is associated with survival of patients with glioblastoma." (PMID 36291588, 2022). "Immunohistopathological analyses identified the lesion as an isocitrate dehydrogenase (IDH) wild-type epithelioid glioblastoma with O6-methylguanine-DNA methyltransferase (MGMT) methylation at 12% and BRAF V600E mutation." (PMID 35130969, 2022). "The suppression of DNA repair protein O6-methylguanine-DNA-methyltransferase (MGMT; associated with treatment resistance in glioblastoma multiforme) using nanoparticles containing MGMT-targeting siRNA duplexes was quantified using non-invasive optical imaging." (PMID 36557793, 2022). "Although methylated MGMT promoter with IDH1 mutant glioblastoma cases showed clinically significant results, the cases with unmethylated MGMT promoter and IDH1 mutation treated with combined chemotherapies had significantly late tumor recurrence." (PMID 34257620, 2021). "The therascreen MGMT Pyro test detects methylated MGMT, which is associated with the treatment response in the case of glioblastoma, and Epi proLung test detects aberrant methylated PTGER4 and SHOX2 in cfDNA from blood plasma in LC." (PMID 33175673, 2021). "For example, EGFR alterations and TERT promoter mutations are associated with poor prognosis, whereas IDH mutations and MGMT promoter methylation are associated with favorable prognosis in glioblastoma patients." (PMID 34732244, 2021). "O-6 methylguanine-DNA methyltransferase expression is associated with DNA-resistant alkylating agents such as temozolomide, the major chemotherapeutic agent used in glioblastoma." (PMID 34210107, 2021). "Epigenetic inactivation of O6-methylguanine DNA-methyltransferase (MGMT) is associated with increased sensitivity to alkylating chemotherapeutic agents in glioblastoma patients." (PMID 33588926, 2021).